SMAD2 (SMAD family member 2)
Diseases named in the same sentence as SMAD2 in open-access papers (continued):
Sharing a sentence is not in itself a finding about the gene and the disease.
tumor (continued). "Furthermore, Ki-67, Nodal, E-cadherin, and Smad2/3 expressions and their phosphorylation levels were identified via Western blotting and IHC analysis in xenograft tumour models." (PMID 37002201, 2023). "TGF-β also inhibits Smad2/anaplastic lymphoma kinase 5 (ALK5)-mediated CD8+ T cell tumor invasion." (PMID 37205317, 2023). "Our results suggested that SHR-1701 might inhibit the SMAD2-dependent TGF-β pathway that contributes to tumor progression and immunosuppressive microenvironment." (PMID 36280870, 2022). "LOH in chromosome 18q containing tumor suppressor genes SMAD2, SMAD4, and DCC is also common as these genes are transcriptional mediators of the transforming growth factor (TGF)-β signaling pathway, which regulates cell growth, differentiation, and apoptosis, and promotes MYC activation." (PMID 35975243, 2022). "On the one hand, it may upregulate the expression of P21 by inhibiting the activation of Smad2/3 (pSmad2/3) to make tumor cells stagnate in the S phase and, thus, inhibit their proliferation." (PMID 35936728, 2022). "In addition, through RNA-sequencing and western blot analysis, we observe that the TGF-β/Smad2/3 signaling pathway is of great importance in the tumor-promoting function of LPCAT1." (PMID 35880567, 2022). "Smad-2 is phosphorylated via TGFβ1/TGFβ1 receptor signaling, which acts in tumor progression." (PMID 35650563, 2022). "Interestingly, KIT also provides protection against tumor-suppressive TGFβ signaling, possibly by reducing the expression of SMAD2." (PMID 35842424, 2022). "GO analysis highlighted terms related to angiogenesis, cell migration, cell proliferation, and inflammation, while transcription factor motif enrichment analysis additionally suggested an activation of interferon (IRF1) and TGF (SMAD2) signaling in tumor-draining LN fLECs." (PMID 35892863, 2022). "Importantly, it has been revealed that MMP-2 expression is positively controlled by Smad2 whilst MMP-9 is modulated via NF-κB p65/p50 transcription signaling in tumor tissues and cells of CRC." (PMID 35308223, 2022). "Similarly, S2/3 dKO also showed an increase in glandular perimeter suggesting that SMAD2/3 also acts as tumor suppressor." (PMID 34638474, 2021). "Actually, Xu's team is the first to illustrate the relationship between snoRNA and HCC, which indicated that snoRNA SNORD113-1 in HCC could inactivate the intracellular phosphorylation of ERK1/2 and SMAD2/3, presenting its tumor-suppressing function." (PMID 34195281, 2021). "In addition, H-Ras modulates EMT and metastasis by TGF-β1-regulated Smad2 nuclear accumulation in spindle tumor cells." (PMID 33637682, 2021). "Moreover, indomethacin prevents the activation of TGFβ/SMAD2/3 signalling and enhances anti‐tumour immune responses." (PMID 34709754, 2021). "Moreover, PSE and Phy resulted in a decreasing level of the TGF-β canonical pathway Smad2/3, which is essential for tumour growth." (PMID 33809098, 2021). "It interacts with SMAD2 and has functions of chromatin reorganization and transcriptional regulation through the Wnt signaling pathway downstream of the TGFβ pathway, indicating its potential role of tumor metastasis and relapse." (PMID 34616428, 2021). "Moreover, indomethacin inhibited the activation of cytokine TGFβ, reduced SMAD2/3 phosphorylation, and increased anti‐tumour immune responses in a humanized mouse model." (PMID 34709754, 2021). "SMAD family member 2 (SMAD2) is overexpressed in BC and promotes tumor progression." (PMID 33916931, 2021). "TGF-β significantly promoted tumor formation, blocking Smad2/3 and/or HIF-1α could significantly decrease tumor size; the greatest inhibitory effect on tumors was observed with knockdown of only HIF-1α." (PMID 34930376, 2021).
tumor (continued). "SMAD2 has been shown to act as a tumor metastasis suppressor in cell lines." (PMID 34367349, 2021). "Some clinical research literature demonstrated Smad2 may be a tumor suppressor indeed, and patients with Smad2 deletion had a worse prognosis." (PMID 34712379, 2021). "miR-27a acts as an oncogen by repressing the expression of the tumor suppressors SMAD2 and SMAD4." (PMID 33498521, 2021). "Thus, PLK1-induced phosphorylation of vimentin is a coordinator of metastatic tumorigenesis in LUAD through activation of TGF-β signaling for metastasis and expression of PD-L1 by p-Smad2/3 for tumor survival." (PMID 33963314, 2021). "Candidate pathogenic mutations in untranslated regions (UTRs) and BC-relevant genes regions, including oncogenes (i.e., KRAS, ERBB3, PIK3C2G) and tumor suppressor genes (i.e., FANCC, ATR, SMAD2), were found in organoids, and the majority of them were conserved within the tumor–organoid pair." (PMID 33371412, 2020). "Phosphorylation of SMAD3 was significantly reduced in the presence of TMEPAI in the muscles of C26 tumor-bearing mice, and TMEPAI expression also attenuated transcriptional activation of SMAD2/3-target genes in C26 tumor-bearing mice, including Cyr61, and Igfn1." (PMID 33250771, 2020). "Levels of total SMAD2/3 protein were also increased in Ahr cKO tumours." (PMID 31924815, 2020). "The increase in total SMAD2/3 protein levels suggests Ahr might also function by either suppressing SMAD2/3 transcription in the tumour context or promoting SMAD2/3 proteolytic turnover." (PMID 31924815, 2020). "We then investigated whether increase of PGC-like tumor cells by SMAD knockout is correlated with enhanced liver metastasis by genetically depleting SMAD2 in 4T1 cells using Cas9/CRISPR editing approach." (PMID 32218989, 2020). "In other reports, SMAD2 was shown to exert tumor suppressor function during tumorigenesis 31,32." (PMID 32226309, 2020). "In addition, an elevated DLEU2 expression promotes tumor aggressiveness by regulating the miR-455/SMAD2 axis in pancreatic cancer." (PMID 32555190, 2020). "Indeed, we observed that higher Zip14 expression coincides with greater SMAD2 phosphorylation in the cachectic gastrocnemius muscles of tumor‐bearing mice compared to control." (PMID 32730698, 2020). "For lung cancer, miR-433 and miR-27a suppresses tumor progression via targeting SMAD2." (PMID 33202380, 2020). "Overexpression of SMAD2 could partly reverse the proliferation and invasion inhibiting effects by miRNA-200b-3p overexpression, thus reflecting the tumor promoting effects of SMAD2." (PMID 33202380, 2020). "Based on our results, for the first time, we can state that tumor suppressive TGF-β signaling pathway is dependent on Smad2 mediated activities and pro-oncogenic TGF-β signaling may dependent on Smad3 mediated activities." (PMID 31798766, 2019). "Furthermore, Smad2/3 knockout rescued impaired cell proliferation in vitro and xenograft tumor formation by GREB1 knockout, suggesting that GREB1 abrogates TGFβ signal-dependent inhibition of cell proliferation." (PMID 31462641, 2019). "Additionally, our results shed light on the activation role of OC cell-derived INHBA in stromal fibroblasts, which was via the p-Smad2 pathway and promoted tumor xenograft growth." (PMID 31827640, 2019). "Interestingly, binding motifs for Hypoxia-inducible factor prolyl hydroxylase 1 (PHD1) and the TGFβ-responsive transcription factor SMAD2 were identified to be significantly enriched in tumor samples." (PMID 31404997, 2019).
tumor (continued). "Monitoring the response of the tumor cells to TGF-β1 by analyzing the phosphorylation status of Smad2 demonstrated an increased phosphorylation status of Smad2 upon TGF-β1 treatment, but the overall amount of protein remained the same in all RCC cell lines tested." (PMID 30863498, 2019). "Mutations of SMAD2 are infrequent in cancer, they are found in a small fraction of colorectal carcinoma, while, on the other hand, SMAD4/DPC4 is considered an important tumor-suppressor gene." (PMID 31238579, 2019). "High Smad2 and Smad4 nuclear expression with or without cytoplasmic staining in urothelial cancer was associated with low tumor grade (p = 0.003, p = 0.048, respectively)." (PMID 31238579, 2019). "Furthermore, it inhibits the expressions of TGF-β, Smad2/3, p-Smad2/3, and Smad4 in tumor tissues, suggesting its inhibitive activities on the TGF-β/Smad pathway." (PMID 31505740, 2019). "In addition, IHC for p-Smad2, p-Smad3 and p-c-Myc was performed on the tumour edge tissues of the PIM1 knockdown mice and control mice to confirm tumour invasiveness." (PMID 29472550, 2018). "TGF-β is thought to induce phosphorylation of Smad2 or Smad3 in LECs as well as in tumor cells." (PMID 30142879, 2018). "Also, B-9-3 remarkably down-regulated TGFβRII and reduced the level of phosphorylated SMAD2/3 in the tumor tissue." (PMID 30079021, 2018). "SMAD2 knockdown via shRNA in KRASmt cells also led to increased tumor growth." (PMID 29018205, 2017). "SMAD4, which lies downstream of SMAD2/3, is known to be an important tumor suppressor." (PMID 28417919, 2017). "Importantly, SMAD4, SMAD3, and other key components of the TGF-β/SMAD signaling pathway (i.e., TGFβr1, TGFβr2, and SMAD2) are found within exosomes isolated from tumor cell lines and from human plasma samples." (PMID 28060758, 2017). "Moreover, JPJD can downregulate the total levels of p-Smad2/3 and Snail and upregulate the levels of Smad2/3 in the cytoplasm but have little effect on the total levels of Smad2/3 in the orthotopic CRC tumor tissues." (PMID 28299321, 2017). "In conclusion, our findings revealed that EMP3 might be a potential target for CD44-high GBMs and highlight the essential functions of EMP3 in TGF-β/Smad2/3 signaling activation and tumor progression." (PMID 27527869, 2017). "Upregulation of LEFTY may serve as a useful clinical marker for the therapeutic effects of progesterone for Em Cas, leading to inhibition of tumor cell proliferation through alteration in Smad2-dependent transcription of cyclin A2." (PMID 29268772, 2017). "Furthermore, the Activin receptor inhibitor sb431542 suppressed Smad2 phosphorylation and promoted tumor sphere formation in NB cells, suggesting that the Activin signal pathway is involved in NB stemness." (PMID 28620148, 2017). "Moreover, increased phospho-Smad2/3 signalling was present in the stroma of the Col7-deificient SCC tumours." (PMID 27515461, 2016). "High expression levels of PEAK1 cause the loss of the anti-proliferative effects of TGF-β and initiate TGF-β-induced proliferation, EMT, cell migration, and tumor metastasis with the presence of fibronectin by switching TGF-β signaling from the canonical Smad2/3 pathway to Src and MAPK signaling." (PMID 27916872, 2016). "Therefore, the down-regulation of Smad2/4 promotes to facilitate the restoration of a normal proliferative phenotype by reducing the metastatic behavior of tumor cells." (PMID 27765040, 2016). "EMT is a process that exerts influence on many molecular, such as TGF-β, E-cadherin, N-cadherin Vimentin, ZEB-1, SMAD-2, SMAD-3, SMAD-7, GLI1 and GLI2; these molecules are closely associated with typical phenotype changes of EMT in tumor cell growth and metastasis." (PMID 25895132, 2015). "Moreover, phosphorylation of Smad2 at the linker region has been reported to alter its action from tumour suppression to tumour promotion." (PMID 25884855, 2015).
tumor (continued). "With pbMOO approach, the functional unknown protein OCIAD2 was also enrolled into a signal pathway “TGFβ1- TGFβR1- SMAD2/3- SMAD4- AR-OCIAD2” in tumor and adjacent microenvironment." (PMID 24949437, 2014). "Recent data support the notion that canonical signaling favours tumor suppression, while non-canonical signaling tips the balance, such that TGFβ switches to become a promoter of tumor growth, invasion and metastasis, overriding the tumor-suppressing activities transmitted via Smad2/3." (PMID 24555435, 2014). "However, studies in vitro revealed that SMAD2 functions as a tumor suppressor of prostate epithelial cells." (PMID 22943793, 2012). "As a further support that inhibin-deficient tumors originate from granulosa cells, the Smad2 recombined allele was readily detectable in the tumor tissues of Smad2flox/-; Inha-/-; Amhr2cre/+ mice, but not in the controls lacking the Cre-recombinase." (PMID 20565978, 2010). "In the epidermis, however, Smad2 has been shown to have tumor suppressor activity." (PMID 20942910, 2010). "Smad4, a co-Smad of Smad2, is known as a tumour-suppressor gene in different cancer types." (PMID 12569386, 2003). "Additionally, we developed novel LiPBAE nanoparticles that efficiently deliver miR-590-3p to established rGBM human xenografts and we identified miR-590-3p as potent tumor suppressor that simultaneously block multiple SMAD2/3 targets, induce tumor regression, and prolong animal survival." (PMID 40301302, 2025). "Additionally, functional studies—such as patient-derived organoids and single-cell sequencing—are essential to elucidate the biological impact of SMAD2, ERBB4, ALK, and CTNNB1 mutations and their roles in tumor heterogeneity, drug resistance, and immune evasion." (PMID 40869017, 2025). "Similarly, lincNMR is induced by TGF-β and associates with Smad2 or Smad3 to promote the expression of APOBEC3B, which may contribute to tumor malignancy." (PMID 38569937, 2024). "Notably, the activation of SMAD2/3 represents a critical element in the regulation of TGF-β and SDF-1 autocrine signaling, which is essential for myofibroblast differentiation, phenotype maintenance, and associated tumor-promoting activities." (PMID 38124183, 2023). "In fibroblasts, SMAD2/3 not only differentially regulate fibrosis and response to antifibrotic drugs but they may also control cell migration, which may be relevant for the formation of the fibrotic tumour microenvironment (TME)." (PMID 36572730, 2023). "In addition, co-immunoprecipitation results have further revealed molecular mechanisms for the role of FOXP3 in tumor proliferation and apoptosis, and an in vivo studies suggested that FOXP3 can inhibit tumor growth by suppressing c-Myc directly or by interacting with the Smad2/3/4 pathway." (PMID 36235242, 2022). "In this way, Smad3 could outcompete Smad2 for preferentially gaining a tumor-promoting function." (PMID 35794621, 2022). "Furthermore, it was speculated that FHL3 can regulate the TGF-β-Smad2/3 axis and inhibit the expression of P27 to enhance tumor proliferation." (PMID 35686099, 2022). "Thus, we hypothesized that HF inhibited the proliferation and activation of CAFs through the TGF-β/Smad2/3 signaling pathway which resulted to inhibit tumor cell migration and invasion." (PMID 36506509, 2022). "We speculated Smad2 may be a tumor suppressor, as reported clinical literature." (PMID 34712379, 2021). "Interestingly, megalin mRNA and protein levels were found to decrease in kidney and gallbladder epithelial cell lines upon in vitro activation of transforming growth factor-beta (TGF-ß1)—SMAD2/3 signaling pathway, which is well known for its tumor-suppressive effect." (PMID 34572758, 2021). "We show that increase of PGC-like cell formation by SMAD2 loss promotes liver metastasis, while genetical depletion of PGC-specific genes or pharmacological inactivation of BMP pathways markedly reduces PGC-like tumor cells leading to the impairment of liver metastasis." (PMID 32218989, 2020).
tumor (continued). "Consequently, TrkB could inhibit the TGF-β-mediated tumor suppressor activity through direct interactions with SMAD2, SMAD3, or SMAD4, as exemplified by c-Myc and Tax." (PMID 32340410, 2020). "The anti-MMP14 inhibitory antibody can inhibit tumor growth, reduce tissue hypoxia, increase macrophage number, and shift cell phenotype towards the more anti-tumor M1-like phenotype due to reduced active TGFβ and SMAD2/3 signaling, hence synergistically enhancing RT effects." (PMID 33050580, 2020). "In the previous study, we examined the effects of TGF-βRI kinase inhibitor on the expression of p-SMAD2, tumor size, and cell proliferation, and we compared the tumor cells at the bone-interface with those in the area far away from the bone but within the same tumor." (PMID 31619018, 2019). "However, high Smad2 expression significantly correlated with the classic tumor morphology and the absence of variant morphological features or divergent differentiation." (PMID 31238579, 2019). "In addition, the tumor inhibition of FOXP3 might be regulated by TGF-β signaling pathway via Smad2/3." (PMID 28903735, 2017). "Together with our results that demonstrated high LEFTY expression in Em Cas of advanced stages and with deep myometrial invasion, it appears that LEFTY may have anti-tumor effects through suppression of aggressive tumor growth by blocking TGF-β/Smad2 action in Em Cas." (PMID 29268772, 2017). "Furthermore, HS-173 treatment decreased p-AKT and p-Smad2 in tumor tissues." (PMID 27793006, 2016). "Therefore, HOXA13 may activate TGF-β signaling by interacting with the MH2 domain of SMAD2/3 to regulate the nucleus-cytoplasm distribution of phosphorylated-SMAD2/3 and promote tumor progression." (PMID 26356815, 2015). "Thus, specifically attenuating SMAD2 under TGFß/hypoxia might have functional roles on macrophages biology and tumor progression." (PMID 26146544, 2015). "SARA mutant mice had decreased levels of Smad2 protein in skin tissue and exhibited a similar tumorigenic phenotype as keratinocyte-specific Smad2-KO mice, indicating that SARA may exert its tumor suppressive effects in part through modulation of Smad2 protein levels." (PMID 25170969, 2014). "In addition, loss of one SARA allele in mice, which express more Smad2 protein than in Smad2+/− mice, only induced tumor formation but not highly malignant progression." (PMID 25170969, 2014). "Therefore, accompanying actions of TGF-β in different circumstances, e.g., in regulating development and differentiation in physiological cell process, and in facilitating cell growth and migration and angiogenesis in cancers, Smad2 exerts dual functions as tumor suppressor or oncogene." (PMID 25166914, 2014). "Thus, we conclude that SARA may play a role in the maintenance of the Smad2 checkpoint activity that is required to block not only tumor formation but also malignant conversion at different threshold concentrations." (PMID 25170969, 2014). "The mutations of TβRII, which promoted tumor cell growth, did not affect Smad2/3 binding." (PMID 25120713, 2014). "Knocking-off experiments have showed that the TGF--induced SMAD3-mediated transcriptional response, was mitigated and enhanced by SMAD3 and SMAD2 knockdown, respectively, and this could be directly correlated with divergence in the regulation of tumor angiogenesis in vivo." (PMID 22952604, 2012). "Therefore, p-Smad2 expression of the tumor cells was evaluated at the invading front." (PMID 21110833, 2010). "Therefore, higher level of activated Smad2 may cooperate with activated Ras to induce spindle cell morphology and invasiveness of tumour cells." (PMID 18781153, 2008). "In tumor‐infiltrated CD8+ T cells prepared from LLC1‐bearing mice, the phosphorylation state of SMAD2/3 exhibited significant time‐dependent variation, with higher phosphorylation levels observed at ZT18." (PMID 41257391, 2026).